RECK (reversion inducing cysteine rich protein with kazal motifs)
Description:
Functions together with ADGRA2 to enable brain endothelial cells to selectively respond to Wnt7 signals (WNT7A or WNT7B). Plays a key role in Wnt7-specific responses: required for central nervous system (CNS) angiogenesis and blood-brain barrier regulation (By similarity). Acts as a Wnt7-specific coactivator of canonical Wnt signaling by decoding Wnt ligands: acts by interacting specifically with the disordered linker region of Wnt7, thereby conferring ligand selectivity for Wnt7. ADGRA2 is then required to deliver RECK-bound Wnt7 to frizzled by assembling a higher-order RECK-ADGRA2-Fzd-LRP5-LRP6 complex. Also acts as a serine protease inhibitor: negatively regulates matrix metalloproteinase-9 (MMP9) by suppressing MMP9 secretion and by direct inhibition of its enzymatic activity. Also inhibits metalloproteinase activity of MMP2, MMP14 (MT1-MMP) and ADAM10.
Synonyms: hRECK; ST15
Tractability: Small molecule: a structure with a bound ligand is known. Antibody: UniProt places it where antibodies can reach, with high confidence; its Gene Ontology location is reachable by antibodies, with high confidence; UniProt predicts a signal peptide or a membrane-spanning region; the Human Protein Atlas places it where antibodies can reach.
Gene: Protein-coding gene on chromosome 9 (36,036,905 to 36,124,455, forward strand). Ensembl gene ENSG00000122707.
Subcellular location: Cell membrane
Subcellular location (Human Protein Atlas): Plasma membrane
Pathways (Reactome):
Metabolism of proteins: Post-translational modification: synthesis of GPI-anchored proteins
Gene Ontology:
Molecular function: endopeptidase inhibitor activity; metalloendopeptidase inhibitor activity; protein binding; coreceptor activity; Wnt-protein binding
Biological process: negative regulation of cell migration; positive regulation of amyloid precursor protein biosynthetic process; positive regulation of amyloid-beta formation; regulation of extracellular matrix organization; blood vessel maturation; extracellular matrix organization; negative regulation of extracellular matrix disassembly; regulation of canonical Wnt signaling pathway; sprouting angiogenesis; canonical Wnt signaling pathway; positive regulation of canonical Wnt signaling pathway; regulation of angiogenesis; regulation of establishment of blood-brain barrier
Cellular component: plasma membrane; extracellular region; plasma membrane raft; Wnt signalosome
Genetic constraint (gnomAD): Loss-of-function variants: 56 observed, 95.23 expected, observed/expected ratio (o/e) 0.59, 90% interval 0.47 to 0.74. The upper end of that interval is the gene's LOEUF score, 0.74, which puts it in group 3 of 6, group 1 being the genes least tolerant of losing a copy. Missense variants: 959 observed, 1,127.9 expected, observed/expected ratio (o/e) 0.85, 90% interval 0.81 to 0.9. Synonymous variants: 387 observed, 394.09 expected, observed/expected ratio (o/e) 0.98, 90% interval 0.9 to 1.07.
Homologues: Orthologues: chimpanzee RECK (98% identical), macaque RECK (96% identical), rabbit RECK (95% identical), pig RECK (95% identical), guinea pig RECK (94% identical), mouse Reck (94% identical), rat Reck (92% identical), dog RECK (91% identical), tropical clawed frog reck (74% identical), zebrafish reck (47% identical), Drosophila melanogaster Reck (33% identical).
Diseases named in the same sentence as RECK in open-access papers:
RECK is named in the same sentence as 137 diseases in open-access papers, as found by Europe PMC text mining. Sharing a sentence is not in itself a finding about the gene and the disease. The quoted sentences say what the papers report.
gastric cancer (25 papers, 2007 to 2024). A primary or metastatic malignant neoplasm involving the stomach. "It was also found that miRNA-222 overexpressed in gastric cancer cells increased the proliferative ability of gastric cancer cells by regulating the expression of RECK." (PMID 37641123, 2023). "Correlation of RECK expression and clinical prognosis in gastric cancer with various clinicopathological factors." (PMID 37255541, 2023). "In the current study, bioinformatics analysis of diverse datasets revealed an aberrant decrease in RECK expression and an antitumour role for RECK as an independent factor contributing to favorable prognosis in patients with gastric cancer." (PMID 37904179, 2023). "Concurrently, the mechanism, involving the interplay between ERK1/2 and CALD1, appeared to contribute to the anticancer effects of RECK in gastric cancer." (PMID 37904179, 2023). "The relationship between the expression of PVT1, hesa-miR-130a-3p and RECK and the prognosis of clinical-pathological features of gastric cancer was further analyzed." (PMID 37255541, 2023). "The findings of this study indicate that the expression of RECK is significantly reduced in gastric cancer." (PMID 37904179, 2023). "Immunohistochemistry (IHC) staining of clinical gastric cancer sample and normal tissue further confirmed the low expression of RECK in GC tissue compared to the normal group." (PMID 37255541, 2023). "It has been reported that miR-25 can also target RECK in gastric cancer to promote cell motility and growth." (PMID 32138716, 2020). "The epigenetic downregulation of RECK is known to stimulate invasion and migration in colon cancer, breast cancer, prostate cancer, lung cancer, and gastric cancer." (PMID 31338326, 2019). "For example, decreased RECK expression has been reported in 81.8 % of 11 gastric cancer cell lines and 52 % of the 102 gastric cancer tissues." (PMID 27530410, 2016). "A large number of tumor cell lines and tissues including colorectal, breast, pancreatic, gastric cancer have low or undetectable RECK expression." (PMID 27530410, 2016). "There is also an obvious inverse correlation between RECK expression and macroscopic tumor growth, lymphatic invasion, lymph node metastasis as well as stage, which suggests that RECK constitutes a good prognostic marker in gastric cancer." (PMID 27530410, 2016). "Translational repression of RECK by miR-222 has already been shown for gastric cancer, and by miR-182 for prostate, breast and bladder cancer, but so far not for NSCLC." (PMID 27588394, 2016). "Enforced expression of miR-21 increases the invasiveness of gastric cancer cells, RECK is the direct target of miR-21." (PMID 23554909, 2013). "The alterations found in CALD1 and CALD1 phosphorylation, which were triggered by RECK, may potentially contribute to the anticancer actions of RECK in gastric cancer cells." (PMID 37904179, 2023). "Furthermore, data collected from cBioPortal showed a 6% deletion of the RECK gene in TCGA gastric cancer cases." (PMID 37255541, 2023). "Hence, these findings implied that the antiproliferative and anti-metastatic impacts of RECK in gastric cancer were ERK-dependent." (PMID 37904179, 2023). "Furthermore, the assessment of RECK expression levels holds promise as a possible indicator for guiding immunotherapy strategies in patients with gastric cancer." (PMID 37904179, 2023). "Consequently, these results suggested that the antiproliferative and anti-metastatic impacts of RECK in gastric cancer were CALD1-dependent." (PMID 37904179, 2023). "When over-expressed, miR-21 could change biological processes of gastric cancer cells such as proliferation, apoptosis, migration, and invasion probably through regulating RECK (a known tumor suppressor in gastric cancer) and other critical target genes." (PMID 33868612, 2021). "MiRNA-25 had been investigated in gastric cancer via targeting RECK, but we found that there might be other targets." (PMID 34764975, 2021).
gastric cancer (continued). "In gastric cancer, miR-25 targets to RECK to promote cancer cell motility and growth." (PMID 32138716, 2020). "Besides, Western blot showed the low expression of RECK in gastric cancer than normal group." (PMID 37255541, 2023). "Moreover, in gastric cancer, overexpression of miR-25 could promote gastric cancer cell proliferation, migration, and invasion via targeting RECK." (PMID 34764975, 2021). "LASSO Cox regression with 10-fold cross-validation for the clinical prognostic effect of gastric cancer identified one lncRNA (PVT1), one miRNA (hsa-miR-130a-3p) and one mRNA (RECK)." (PMID 37255541, 2023). "Gastric cancer samples harboring shallow deletions showed no differential expression of RECK in comparison to diploid, amplification or gain samples." (PMID 37255541, 2023). "Similar results obtained in HCC and CCA patients were found in other cancers such as patients with gastric cancer, colorectal cancer, and pancreatic cancer: a significant negative correlation was found between RECK and MMP-2/MMP-9 expression." (PMID 38139236, 2023). "In Gastric Cancer (GC), its upregulation may lead to the suppression of tumor-suppressor genes, including PTEN, RECK, and PDCD4, and promote proliferation, migration, and apoptosis inhibition." (PMID 32258003, 2020). "Moreover, in gastric cancer cells, ADAM10 and ADAM17 are pulled down together by RECK - suggesting a physical interaction between RECK and ADAMs at the cell surface." (PMID 25246708, 2014). "So far miR-21 and miR-222 have been found to target RECK in prostate cancer and gastric cancer but there have been no reports about miR-182-5p and RECK." (PMID 23383207, 2013). "Furthermore, in gastric cancer patients with a variety of clinicopathological features, such as T stage 2 or 4 or N+ stage, M0 stage, surgery, 5-FU-based adjuvant therapy, other adjuvant therapy, and negative HER2, increased RECK expression was linked to a worse prognosis (p < 0.05)." (PMID 37255541, 2023).
breast carcinoma (24 papers, 2008 to 2023). "The proteins encoded by the PDCD-4, FasL, PTEN and RhoB genes are related to the regulation of breast cancer cell proliferation, and the proteins encoded by the Maspin, TIMP3 and RECK genes are related to the regulation of breast cancer cell invasion." (PMID 38041032, 2023). "Walsh and collaborators reported that RECK+ is associated with a threefold decrease in IL-8 mRNA levels and that RECK can physically bind to IL-8 in a breast cancer model." (PMID 34066355, 2021). "Seventh, RECK CpG methylation, especially RIM, correlates with higher tumor stages and histological grades, supporting the idea that the RECK silencing (associated with RIM) contributes to the malignant behaviors of breast cancer cells." (PMID 27058625, 2016). "Previously, RECK was shown to be physically associated with IL-6R and gp130 in breast cancer cells." (PMID 37830075, 2023). "An inverse association between miR-182 and RECK was demonstrated in breast cancer tissues." (PMID 24670365, 2014). "However, the association between RECK expression and the outcome of breast cancer patients remains unclear." (PMID 26449734, 2015). "After the transfection of siEmi1 mimics, the mRNA levels of the invasion-related genes Maspin, TIMP3 and RECK in breast cancer cell strains were significantly reduced." (PMID 38041032, 2023). "This indicated that Emi1 KD can regulate the invasion-related genes Maspin, TIMP3 and RECK in breast cancer cells." (PMID 38041032, 2023). "Walsh and his colleagues found that RECK can participate in metastasis of breast carcinoma via regulation of STAT3‐dependent switch." (PMID 37795791, 2023). "Studies have shown that DPYSL2 affects tumor cell migration via its effect on microtubules; however, it impedes stemness and metastasis of breast cancer cells when combined with RECK." (PMID 34517904, 2021). "In previous studies, regulation of RECK by DNA methylation has been described and proposed as a potential marker for predicting breast cancer prognosis." (PMID 32051475, 2020). "Five of the twenty eight ceRNA hubs were common to all the four breast cancer subtype networks, including RECK, which controls breast cancer metastasis by regulating MMP-2 (matrix metalloproteinases-2) to inhibit tumor angiogenesis." (PMID 28052038, 2017). "A previous methylome study on breast cancer tissues detected inverse correlation between RECK CpG methylation (in an intron-1 region) and relapse-free survival." (PMID 27058625, 2016). "In the present work, we measured RECK protein levels both in a panel of human breast cell lines and in a large series (1040) of breast cancer cases, allowing a more significant conclusion." (PMID 26449734, 2015). "We evaluated RECK protein expression levels in a large series (n = 1040) of breast cancer cases by immunohistochemistry on TMAs." (PMID 26449734, 2015). "In this cell culture model, RECK continues to act as an invasion inhibitor via MMP down-modulation even in highly invasive human breast cancer cells." (PMID 26449734, 2015). "The available data indicated that lower RECK mRNA levels were expressed in tumor tissue samples than in normal breast tissue samples, and higher levels were found in invasive human breast cancer cells than in less aggressive ones." (PMID 26449734, 2015). "This indicates that TGF-β1 have opposite effects over RECK mRNA and protein levels in breast cancer cells." (PMID 26247610, 2015). "We observed that more invasive cells (T4-2, MDA-MB-231 and Hs578T) displayed significantly higher (p < 0.05, p < 0.01 and p < 0.001, respectively) RECK protein levels than non-invasive breast cancer lineages (MCF-7 and T47D)." (PMID 26449734, 2015). "In contrast to other tumor types, RECK expression cannot predict breast cancer patient survival, although its inhibitory function in invasion has been confirmed." (PMID 26449734, 2015).
breast carcinoma (continued). "Others have previously reported that in both breast tumors and cell lines, there is a negative association between the expression of MMP-9 and one of its natural inhibitors, RECK, a key breast cancer metastasis suppressor gene." (PMID 25668816, 2015). "A retrospective study using 119 cases of breast cancer samples, suggests, similar to other cancer types, that a low expression of RECK indicates a shorter survival rate for patients with invasive breast cancer." (PMID 26449734, 2015). "RECK protein levels were also analyzed in 1040 cases of breast cancer using immunohistochemistry and tissue microarrays (TMAs)." (PMID 26449734, 2015). "The RECK protein expression levels were analyzed in a large series (1040) of breast cancer cases using immunohistochemistry of tissue microarrays (TMAs)." (PMID 26449734, 2015). "Conversely, another report demonstrated not only higher RECK levels in invasive breast cancer cell lines than in the non-invasive one but also a positive correlation between RECK and MMP expression in tumor tissue samples." (PMID 26449734, 2015). "Taken together, the results obtained demonstrate that TGF-β1 is a common regulator of MMPs (MMP-2 and MMP-9) and their inhibitors (TIMP-2 and RECK) in breast cancer cell models." (PMID 22260435, 2012). "In the present study, we investigated the role of TGF-β1 as a common regulator for MMPs, TIMPs and RECK in highly invasive human breast cancer cells and the involvement of the ERK1/2 and p38 MAPK pathways in this mechanism." (PMID 22260435, 2012). "For this reason, we first analyzed the mRNA expression levels of MMP-2, MMP-9, MMP-14, TIMP-1, TIMP-2, TIMP-3 and RECK, in the same panel of five human breast cancer cell lines, but now maintained in culture until achieving 80-90% confluence." (PMID 22260435, 2012). "Here we analyzed the involvement of ERK1/2 and p38 MAPK, two well established Smad-independent pathways, in the proposed mechanism of coordinate regulation of MMPs, TIMPs and RECK by TGF-β1 in breast cancer cell lines." (PMID 22260435, 2012). "In this report, we demonstrated, for the first time, that TGF-β1 is able to modulate MMP, TIMP and RECK expression in MDA-MB-231 human breast cancer cell line through ERK1/2 and p38MAPK." (PMID 22260435, 2012). "Due to these functions, RECK has been described as a good prognosis marker in several tumor types, including breast carcinomas." (PMID 19144199, 2009). "Cluster 110 contains genes that have previously been associated with chemotaxis and invasion of breast cancer cell lines (SLIT2, RECK), as well as genes related to the extracellular matrix (ECM2, COL4A1)." (PMID 18498629, 2008). "In clinical samples (n=62), RECK intron-1 methylation was prevalent among luminal breast cancers (26 of 38 cases; 68%) and particularly enriched in tumors of the ER+PR- subclass (10 of 10 cases) and of higher histological grades (Grade 2 and 3; 28 of 43 cases; P=0.006)." (PMID 27058625, 2016). "Importantly, in a non-biased, genome-wide methylation study, Hill and colleagues detected RECK as one of several loci whose methylation inversely correlated with relapse-free survival among breast cancer patients." (PMID 27058625, 2016). "Furthermore, we investigated RECK function in mammary neoplasia using RECK-silenced human breast cancer cells, obtained by RNA interference methodology." (PMID 26449734, 2015). "However, despite the extensive amount of work addressing the RECK prognostic value for prostate, lung and pancreatic tumors, RECK function and expression profile in breast cancer remain an open question." (PMID 26449734, 2015). "Therefore, our results suggest that, unexpectedly, human breast cancer cells with a higher invasive potential express elevated levels of RECK." (PMID 26449734, 2015).